CTLA4 (cytotoxic T-lymphocyte associated protein 4)
Diseases named in the same sentence as CTLA4 in open-access papers (continued):
Sharing a sentence is not in itself a finding about the gene and the disease.
melanoma (continued). "In the last decade, immunotherapeutic strategies that inhibit CTLA-4 and PD-1/PD-L1, the well-known immunological checkpoints, have shown remarkable success in the treatment of cancer, especially melanoma and Hodgkin’s lymphoma." (PMID 36508191, 2023). "Here, we provide mechanistic insights into the downregulation of CTLA4 expression in Treg cells from melanoma through miR-155." (PMID 37197667, 2023). "Immune checkpoint blocking by monoclonal antibodies appeared as a successful treatment for patient with melanoma which targets cytotoxic T lymphocyte antigen (CTLA-4) directly, for instance, Ipilimumab that targets PD-1 and PDL-1." (PMID 37605149, 2023). "Ipilimumab is considered the first FDA approved anti-CTLA4 monoclonal antibody used in treatment of melanoma." (PMID 38313431, 2023). "Here, we investigated the mechanisms and the immune cells involved in the response to a triple combination therapy including guadecitabine and two ICBs (anti-CTLA-4 and anti-PD-1 mAbs) in a SC and a pseudo-metastatic syngeneic mouse model of melanoma." (PMID 36934257, 2023). "We observed a significant decrease in the CTLA4 levels in Treg cells from melanoma patients, which were almost equivalent to the levels observed in Tconv cells." (PMID 37197667, 2023). "Recently, the LFA‐1 agonist 7HP349 was in a clinical trial to treat patients with non‐immunogenic melanoma via combination treatment with CTLA‐4 blockade." (PMID 37097643, 2023). "Ipilimumab, a human cytotoxic T-lymphocyte antigen 4 (CTLA-4)-blocking antibody indicated for the treatment of advanced melanoma, was the first ICI that received approval, opening a new era in cancer immunotherapy." (PMID 37046762, 2023). "Patients receiving anti PD-1/anti-CTLA-4 combination therapy were younger (p = 0.043) and exclusively treated for melanoma (p = 0.003), when compared to patients receiving anti PD-1 monotherapy." (PMID 37297945, 2023). "Although ICIs, particularly anti-CTLA4 and anti-PD-1 antibodies, have radically improved the prognosis of many cancers, especially advanced melanoma, they have been less effective in BC patients." (PMID 38239641, 2023). "Compared to previously dismal outcomes with a median survival of <1 year, studies of anti-PD-1 monotherapy and combination anti-CTLA-4/PD-1 therapy in advanced melanoma have reported 6.5-year-overall survival (OS) rates of 42% and 49%, respectively." (PMID 37903733, 2023). "Heat-inactivated MVA recombinant also generates stronger immunity and anticancer effect than a live counterpart when combined with anti-CTLA4 or anti-PD-L1 antibody in a murine melanoma model." (PMID 36755342, 2023). "Accordingly, combination of guadecitabine with antibodies directed against CTLA-4 (ipilimumab) has already been tested in human melanoma patients (NIBIT-M4 trial, NCT02608437)." (PMID 36934257, 2023). "Combining CTLA-4 and PD-1 inhibition enhances survival in patients with melanoma, renal cell carcinoma, and a variety of other cancers." (PMID 37232823, 2023). "Objective response rates (ORR) for advanced melanoma or renal cell carcinoma (RCC) patients treated with dual immune checkpoint blockade (anti-CTLA-4 and anti-PD-1) are 57.6% and 42%, respectively." (PMID 37964379, 2023). "GSE91061, which including 109 melanoma samples with anti-CTLA4 and anti-PD1 therapy demonstrated patients with complete response (CR) or partial response (PR) had a lower riskscore than those with stable disease (SD) or progressive disease (PD)." (PMID 37592010, 2023). "Engineered nanoparticles carrying immunostimulatory oligonucleotides has been confirmed to synergize with anti-CTLA-4 therapy to achieve tumor suppression in animal models of melanoma, colon cancer, and breast cancer." (PMID 37386520, 2023).
melanoma (continued). "Specific alterations (deletions, point mutations, or loss of heterozygosity) in the essential components of the MHC class I, such as beta-2-microglobulin, are found more frequently in patients with melanoma unresponsive to anti-PD-1 or anti-CTLA4 treatment." (PMID 37370782, 2023). "More strikingly, the data from a melanoma cohort treated with anti-CTLA4 antibody showed that patients with lower levels of DNAJA2 expression were greatly benefitted from the therapy than those with higher levels of DNAJA2 expression." (PMID 37640708, 2023). "These cells express PD1 and ICOS, similar to the ICOS+PD1+ Th1-like population that was expanded upon CTLA-4 blockade in melanoma patients." (PMID 37185301, 2023). "Treatment with ipilimumab in melanoma patients has been shown to decrease the abundance of ILC1s and ILC2s in the periphery, whereas the expression of CTLA-4 was reduced in ILC3s and upregulated in ILC1s." (PMID 36765891, 2023). "Combined ICI therapy using the anti-PD-1 antibody nivolumab and the anti-CTLA-4 antibody ipilimumab has been demonstrated to increase the tumor infiltration with T-cells in melanomas." (PMID 37569431, 2023). "Immune checkpoint inhibitors, whose main targets are programmed cell death protein 1 (PD1), programmed cell death 1 ligand 1 (PDL1), and cytotoxic T-lymphocyte-associated protein 4 (CTLA-4), have been successfully used in the treatment of melanoma." (PMID 36875110, 2023). "Clinical evidence has showed that combining oncolytic viruses with checkpoint inhibitors CTLA-4 in various cancer types, including prostate, and melanoma xenografts, resulted in upregulation of intratumoral T cells and boosting T cell immunity to solid tumors." (PMID 36766849, 2023). "The pre-clinical version of the GVAX-GM-CSF vaccine was the immediate solution to unleash immunogenicity for anti-CTLA-4 blockade in this melanoma model." (PMID 37454231, 2023). "For example, therapeutic anti-CTLA-4 monoclonal antibody drugs have shown remarkable clinical efficacy in treating melanoma." (PMID 37284202, 2023). "Currently, both, anti-PD-1 monotherapy and combination therapy of anti-PD-1 and anti-CTLA-4 are applied in the treatment of melanoma." (PMID 37259155, 2023). "Five-year overall survival (OS) of patients with melanoma exhibiting distant metastasis (stage IV), treated with anti-PD-1 Ab or anti-PD-1 + anti-CTLA-4 Ab, has been reported at 40% and 50%, respectively." (PMID 37046775, 2023). "Patients with melanoma treated with anti‐CTLA‐4 plus anti‐PD‐1 had a higher incidence of irAEs (90.0%, 9 of 10) than those with renal cell carcinoma (66.2%, 51 of 77)." (PMID 37986680, 2023). "The relationship between USP28 and anti-CTLA4 therapy response in patients with melanoma tumors revealed that low-expression USP28 patients outlived high-expression patients in terms of survival rate and time." (PMID 37450415, 2023). "Currently, anti-CTLA-4 monoclonal antibodies (mAbs) are widely used in the treatment of multiple solid cancers, including melanoma, renal cell carcinoma, and colorectal cancer." (PMID 37576404, 2023). "Clinical trials have shown that combination therapy with anti-PD-1 and anti-CTLA-4 is effective in treating lung cancer and melanoma." (PMID 36969851, 2023). "Similar findings were observed using T-cell targeting 89Zr-labeled PEGylated single-domain antibody fragments (VHHs) specific for CD8+ to track the presence of intratumoral CD8+ T cells in response to CTLA-4 therapy in B16 melanoma tumor-bearing mice." (PMID 36266600, 2023). "In previous studies, patients with primary or metastatic urothelial cancer, breast cancer, and melanoma were treated with single or combined monoclonal antibodies against PD-L1, PD-1, and CTLA-4, and the clinical outcomes suggest a protective role for TAP1." (PMID 36759763, 2023).
melanoma (continued). "These therapies have prolonged progression-free and overall survival in melanoma patients, with a median overall survival (OS) of 49% and a melanoma-specific survival of 56% at 6.5 years for patients treated with a combination of CTLA-4 and PD-1 inhibition." (PMID 37509357, 2023). "ICIs targeting CTLA-4 and PD-1 have revolutionized the treatment of melanoma and more generally, solid cancers." (PMID 36765891, 2023). "A study of patients with melanoma treated with CTLA-4 inhibitors suggested that the increase in MDSCs was associated more often with non-responders." (PMID 38263984, 2023). "In a multicenter study, 33% of patients with advanced melanoma with AD which received a combination of anti-CTLA-4 and anti-PD-1 treatment developed a flare, most commonly rheumatic or gastrointestinal irAEs." (PMID 37342323, 2023). "One retrospective study in humans showed the outcomes of 21 patients with advanced melanoma treated with ipilimumab, a CTLA-4 inhibitor, followed by RT." (PMID 37296981, 2023). "An autopsy study in two patients with melanoma who both had died from fatal myocarditis and myositis after treatment with a combination of CTLA-4 and PD-1 inhibitors showed shared T-cell clones in the tumor, heart, and skeletal muscle but not in smooth muscle." (PMID 37089888, 2023). "Previous studies have reported improved responses to combined PD-1 and CTLA-4 blockade in melanoma BrM." (PMID 37655659, 2023). "The United Kingdom’s National Guidelines for Head and Neck Melanoma recommended anti-PD-1 and anti-CTLA4 combination therapy for advanced and metastatic melanoma." (PMID 38139110, 2023). "in melanoma mice lead to enhanced antitumoral effects and improved response to anti-CTLA-4 treatment." (PMID 37705980, 2023). "The introduction of checkpoint inhibitors, such as anti-PD1 and anti-CTLA4 approaches, resulted in a breakthrough step in the outcome of advanced melanoma." (PMID 37568785, 2023). "According to a previous study, higher serum CTLA4 level was correlated with melanoma response and clinical benefit from ipilimumab therapy, but the work is greatly limited due to a very small sample size." (PMID 36397666, 2023). "One of the first studies about these strategies in melanoma patients evaluated retreatment with anti-CTLA4 in melanoma patients, with a follow-up of more than 5 years." (PMID 36986683, 2023). "Direct cytotoxicity of CD4+ CTLs against tumor cells was initially reported in melanoma patients treated with ipilimumab, a monoclonal antibody targeting CTLA-4." (PMID 38077321, 2023). "One patient with malignant melanoma who was treated with an anti-CTLA4 agent at our institution exhibited bilateral serous retinal detachments (SRDs) 22 days after treatment." (PMID 37072549, 2023). "Although PRDX6, MAGOHB, NUCKS1, DCAF13, and TXN genes as a panel displayed weak prediction of ICB response, the panel robustly stratified overall survival in patients with melanoma treated with anti-PD1 following progression on anti-CTLA4 therapy." (PMID 37835514, 2023). "The study group was comprised of patients with advanced melanoma with the goal of studying tumor responses to either anti-PD-1 therapy, or anti-PD-1 therapy combined with anti-CTLA4." (PMID 37691856, 2023). "Lastly, we observed in inverse relationship between baseline and on-treatment levels of circulating LAG3-expressing CD8 memory T cells and response to combination PD-1 and CTLA4 blockade in a clinical trial cohort of patients with melanoma." (PMID 37795090, 2023). "While the expression patterns of CTLA-4 and PD-1 on NK cells and the role of this subset in melanoma immunotherapy are well known, similar knowledge for helper ILCs is still in its infancy." (PMID 36765891, 2023). "The application of anti-CTLA-4 antibodies like Ipilimumab, and anti-programmed cell death 1 (PD-1) antibody-like Nivolumab have led to a long-term disease control in melanoma patients." (PMID 37229449, 2023).
melanoma (continued). "T-VEC has been approved for use in the treatment of patients with advanced melanoma and has been shown to be safe and effective when combined with checkpoint inhibitors, including anti-PD-1 and anti-CTLA-4 antibodies." (PMID 37621406, 2023). "A2AR antagonism was proven to significantly enhance the antitumor activity of anti-CTLA-4 in colorectal, renal, melanoma, prostate and metastatic breast cancer models." (PMID 37753093, 2023). "PD-1/PD-L1 and CTLA-4 inhibitors have shown varying degrees of drug resistance in the treatment of melanoma patients." (PMID 37495610, 2023). "The remarkable clinical results of ipilimumab, a CTLA-4 blocker, and its subsequent approval for the treatment of melanoma, opened a new era in immune-oncology." (PMID 37110545, 2023). "Comprehensive profiling of the effect of checkpoint blockade against tumor immune infiltrates in mouse tumor models and human melanoma has demonstrated that anti-PD-1 and anti-CTLA-4 induce exhausted CD8+ T cell subsets." (PMID 38328405, 2023). "Ipilimumab, an ICI that selectively targets CTLA-4 and has shown promising results in the treatment of melanoma, was the first ICI approved by the FDA for use in cancer immunotherapy." (PMID 38130714, 2023). "Co-targeting RANKL and PD-1 effectively inhibits experimental RM1 prostate cancer and B16F10 melanoma metastasis to the lungs and improves the effectiveness of combined anti-CTLA-4 and anti-PD-1 therapy." (PMID 37929901, 2023). "In patients with advanced melanoma treated with ipilimumab (anti–CTLA-4 agent), elevated LDH levels have been shown to be predictive of poor long-term survival outcomes." (PMID 37773115, 2023). "In this study, we studied the autofluorescence of immune cells in fresh fragments of the lymph nodes during anti-CTLA-4 therapy of mice with B16F0 melanoma at an early stage of treatment by means of the FLIM method." (PMID 38435479, 2023). "The NIBIT-M4 trial was designed to assess the safety, biological and clinical activity of anti-CTLA4 ipilimumab with the DNA hypomethylating agent guadecitabine in advanced melanoma patients." (PMID 37739939, 2023). "Data regarding elderly melanoma patients treated with anti-PD-1 or anti-CTLA-4 antibodies are in favor of tolerability outcomes that are similar to those of younger counterparts." (PMID 37686606, 2023). "This was based on their previous studies, showing that the methylation status of the CTLA4 gene predicts response to both anti-PD-1 and anti-CTLA-4 targeted ICB as well as anti-CTLA-4 monotherapy in patients with melanoma." (PMID 37370768, 2023). "High MYB expression is related to worse outcomes of anti-PD-1+ anti-CTLA4 treatment in melanoma, while received good outcomes of anti-PD-1 treatment in kidney cancer, melanoma, bladder cancer and glioblastoma." (PMID 36994664, 2023). "In melanoma patients treated with CTLA4 or PD1 ICB, both Overlap36 and Overlap36sub stratify poor OS; among the 9 published signatures, Overlap36sub is the only one stratifying poor OS in clear cell renal cell carcinoma treated with ICB." (PMID 36588164, 2023). "The combination of anti-CTLA-4 and anti-PD-1 treatment appears to target separate populations of T-cells and has already been approved in hepatocellular carcinoma, melanoma, renal cell carcinoma, and colorectal cancer, with a variety of trials ongoing." (PMID 37386520, 2023). "Previous investigations have demonstrated robust tumor immunity against murine melanoma obtained by combining DNA vaccination with dual CTLA-4 and PD-1 blockade." (PMID 37445686, 2023). "A study of 34 melanoma patients treated with anti-CTLA4 (ipilimumab) with some specific microbes from the Bacteroidetes phylum were associated with a reduced risk of colitis." (PMID 36986683, 2023). "Antibody-based cancer drugs that target the checkpoint proteins CTLA-4, PD-1 and PD-L1 provide marked improvement in some patients with deadly diseases such as lung cancer and melanoma." (PMID 38069222, 2023).
melanoma (continued). "The anti-CTLA4 antibody tremelimumab was also evaluated as a potential treatment for advanced melanoma." (PMID 36831449, 2023). "For instance, patients with advanced melanoma refractory to anti-PD-1 therapy who receive adoptive transfer of tumor infiltrating lymphocytes (TILs) have better survival compared with anti-CTLA-4 blockade." (PMID 37459511, 2023). "In this work, we developed a mathematical model to investigate the treatment of murine model of malignant melanoma B16-CD20 using an immune checkpoint inhibitor anti-CTLA-4 and OVT." (PMID 36766849, 2023). "It has been shown that autophagy suppression contributes to CTLA-4 inhibition resistance in melanoma." (PMID 37189748, 2023). "It should be noted that pathway inhibitors have shown a potential synergistic effect with other antitumor agents in melanoma such as checkpoint inhibitors and anti-cytotoxic T-lymphocyte antigen 4 (CTLA-4) antibodies." (PMID 36844227, 2023). "The stimulation of the immunological response in melanoma was also obtained by the inhibition of Cytotoxic T-Lymphocyte Antigen 4 (CTLA-4), an immunoglobulin cell surface receptor, able to inhibit T-cell activation." (PMID 36978794, 2023). "So, we tested the predictive value of the RiskScore in the melanoma combined anti-PD-1 and anti-CTLA-4 immunotherapy data sets." (PMID 37521469, 2023). "Our findings are in line with a previous study that observed neutrophil enrichments in melanoma tumors failing to respond to either anti-CTLA-4 or anti-PD-1 therapy." (PMID 37372107, 2023). "CTLA4 inhibition results in a high incidence of dose-dependent toxicities, and 38.6-57.9% of patients with melanoma who received ipilimumab developed high-grade toxicities." (PMID 37033964, 2023). "Clinical trials have also confirmed that the effectiveness of targeted drugs such as CTLA-4 and PD-1 alone or in combination with other drugs is limited for patients with advanced GC, which is far less than that of melanoma, lung cancer and other tumors." (PMID 38026944, 2023). "Alternatively, the expression of the immune checkpoint, PD-1/PD-L1 and CTLA4, was augmented in the melanoma cells with the knockdown of RAC1." (PMID 37217516, 2023). "Recent research even indicated that the combination of PD-1 and CTLA-4 blockade was more effective than either agent alone in melanoma, highlighting the need for biomarkers for combination regimens." (PMID 37259026, 2023). "In the B16 melanoma model system, it has been shown that targeting intratumoral Tregs, using CTLA-4 antibodies, offers tumor protection when combined with CD8 T-cell inducing vaccination." (PMID 36968226, 2023). "Anti-CTLA-4 antibody ipilimumab was the first drug to show a significant improvement in overall survival in the treatment of advanced melanoma, and its use in this setting was approved in 2011 by the Food and Drug Administration (FDA)." (PMID 37404764, 2023). "Among the types of immunotherapies, anti-CTLA-4 antibodies, like ipilimumab, have shown effectiveness in treating melanoma and renal cell carcinoma." (PMID 37958483, 2023). "This leads to an ineffective T-cell response and, in turn, resistance to T-cell-based immunotherapies, such as anti-PD-L1 and anti-CTLA-4, in melanoma." (PMID 38139110, 2023). "Anti-CTLA4 and anti-PD-1 therapy have demonstrated the therapeutic promise of overall 5-year survival in advanced melanomas, with the curtailment of brain metastases." (PMID 36834917, 2023). "We further analyzed the expression level of SNAI2 and response to anti-PD-L1 immunotherapy in urological tumors, and anti-PD1 and anti-CTLA4 in melanomas." (PMID 37251370, 2023). "Numerous studies have shown that the TIDE score accurately predicts outcomes for patients with melanoma treated with anti-PD1 or anti-CTLA4." (PMID 37509156, 2023). "Our working group has already published experiences about the application of the CTLA4 inhibitory strategy in melanoma." (PMID 37568785, 2023).